IFNAR1 (interferon alpha and beta receptor subunit 1)
Diseases named in the same sentence as IFNAR1 in open-access papers (continued):
Sharing a sentence is not in itself a finding about the gene and the disease.
Listeria infection (9 papers, 2009 to 2023). "Furthermore, the survival curve of mice with myeloid cell-specific IFNAR1 ablation suggests that cells outside this cell compartment influence the survival of Listeria infection particularly after the innate phase of the immune response." (PMID 19325882, 2009). "Mice deficient in IFNAR1 (Ifnar1−/−) have reduced pathogen loads in response to intracellular bacterial infection, and administration of type I IFN-inducing poly: (IC) exacerbates listeriosis and tuberculosis (TB) in wild-type (WT), but not Ifnar1−/− mice." (PMID 29311663, 2018).
Thrombocytopenia (9 papers, 2016 to 2026). A reduction in the number of circulating thrombocytes. "Necroptosis‐independent RIPK3 function contributes to anemia, while co‐deletion of Ifnar1 rescues anemia, thrombocytopenia, and splenomegaly, highlighting ABIN1 (Q478) as a regulator of hematopoietic deficiencies through type I IFN expression." (PMID 38009796, 2024). "Consistently, blocking type I IFN signaling through the co‐deletion of Ifnar1 greatly ameliorated anemia, thrombocytopenia, and splenomegaly in Abin1Q478H/Q478H mice." (PMID 38009796, 2024). "Furthermore, our experimental results demonstrate that the knockout of IFNAR1 can both rescue anemia and alleviate thrombocytopenia symptoms." (PMID 38009796, 2024). "However, the co‐deletion of Ifnar1, which blocks type I IFN signaling, greatly ameliorated anemia, thrombocytopenia, and extramedullary hematopoiesis in these mutant mice." (PMID 38009796, 2024).
colon carcinoma (8 papers, 2017 to 2025). "To determine whether the differential effects of STAT2 and IFNAR1 deletion observed in human cells were conserved in a murine context, we evaluated STAT2- and IFNAR1-deficient mouse MC38 colon carcinoma cell lines." (PMID 41440237, 2025). "Together, these results indicate that, like the human model, loss of STAT2 or IFNAR1 disrupts IFN-I-dependent transcription, although the downstream signaling consequences differ between the two genes in murine colon carcinoma cells." (PMID 41440237, 2025). "Together, these results demonstrate that, despite their shared involvement in IFN-I signaling, STAT2 and IFNAR1 exert opposing effects on colon cancer cell proliferation and tumor progression." (PMID 41440237, 2025). "Our findings demonstrate that STAT2 functions as a tumor-promoting factor in colon cancer, acting independently of canonical IFNAR1-mediated type I interferon signaling." (PMID 41440237, 2025). "In this study, we provide experimental evidence that STAT2 plays a tumor-promoting role in colon cancer that is distinct from the canonical, tumor-suppressive effects of IFNAR1-mediated IFN-I signaling." (PMID 41440237, 2025). "We also observed that the PD-1 expression level is also positively correlated with the expression levels of IFNB1 and IFNAR1 in the myeloid cells of human colon cancer patients." (PMID 38995014, 2024). "Analysis of TCGA dataset revealed that the IFNAR1 expression level is significantly down-regulated in human colon carcinomas as compared to the normal colon tissues." (PMID 31228946, 2019). "We observed here that the IFNAR1 is significantly down-regulated in both the colon carcinoma tissues and CTLs of colon cancer patients as compared to the normal colon tissues and CTLs of healthy donors, respectively." (PMID 31228946, 2019). "Our findings indicate that IFNAR1 is potentially a therapeutic target for boosting CTL effector function in human colon cancer immunotherapy." (PMID 31228946, 2019). "To determine whether this function depends on type I IFN receptor (IFNAR1) signaling, we generated IFNAR1 knockout (IFNAR1 KO) colon carcinoma cells and compared their growth with parental and STAT2-deficient (STAT2 KO) tumor cells." (PMID 41440237, 2025). "We provide evidence that human colon carcinoma cells may use down-regulation of IFNAR1 to impair CTL effector function to evade host cancer immunosurveillance." (PMID 31228946, 2019). "Because IFNAR1 mediates all isoforms of IFN-I signaling, our above findings suggest that human colon carcinoma might use down-regulating IFNAR1 to impair IFN-I signaling in CTLs to evade immune surveillance." (PMID 31228946, 2019). "It becomes critically important to determine whether IFN-I plays a role in CTL function in the tumor suppression since the IFNAR1 is down-regulated on CTLs from human colon cancer patients." (PMID 31228946, 2019). "Therefore, human colon carcinoma may use down-regulating IFNAR1 in CTLs as a mechanism to impair CTL effector function to evade host cancer immunosurveillance." (PMID 31228946, 2019). "The tumor tissue is a mixture of tumor cells and immune cells, we then compared IFNAR1 protein level on CD8 + T cells from healthy donors and colon cancer patients." (PMID 31228946, 2019). "Studies using human colorectal carcinoma cells have shown that tumor tissue and CTLs from colon cancer patients have decreased expression of IFNAR1 compared to normal colon tissue and CTLs from healthy donors." (PMID 33801234, 2021). "Therefore, targeting IFNAR1 down-regulation is potentially an effective approach to bypass both PD-L1-depedent and PD-L1-independent immune suppressions to directly activate CTL effector function to suppress colon carcinoma growth." (PMID 31228946, 2019).
measles (8 papers, 2020 to 2026). A highly contagious viral infection caused by the measles virus. "AR complete IFNAR1 deficiency was discovered in a 9-yr-old Iranian boy who suffered severe measles, mumps, and rubella (MMR) vaccine disease at the age of 1 yr." (PMID 35442418, 2022). "The impact of IFNAR1 deficiency in this recent epidemic—or in the 1893 Samoan measles epidemic, which resulted in ≥1,000 deaths in a population of 34,500 (Davies, 1894)—is unknown." (PMID 35442418, 2022). "Individuals with IFNAR1 deficiency have a predicted high susceptibility to the WT measles virus, so a small fraction of severe WT measles cases may actually be due to IFNAR1 deficiency." (PMID 35442418, 2022). "Paradoxically, there was also a report showing no adverse sequelae in humans with genetic defects in both the IFNAR1 and IFNGR2 genes after attenuated measles vaccination." (PMID 32300346, 2020).
Alzheimer disease (7 papers, 2016 to 2025). A progressive, neurodegenerative disease characterized by loss of function and death of nerve cells in several areas of the brain leading to loss of cognitive function such as memory and language. "This goes along with a report in an in vivo murine model of Alzheimer’s disease instead where IFNAR1 neutralization decreased neuronal synaptic loss, but did not modify the number of β-amyloid plaques accumulated in the brain." (PMID 40936901, 2025). "In addition, STAT3 was found to be phosphorylated in an IFNAR1-dependent manner in a model of Alzheimer’s disease, identifying STAT3 as a crucial downstream effector of type-1 IFN signaling." (PMID 27022620, 2016). "Both human Alzheimer's disease (AD) and in vitro and in vivo models of AD show increased IFN‐I expression, and in vivo studies showed decreased pathology and altered microglial phenotype in IFNAR1−/− × APPSWE/PS1ΔE9 mice." (PMID 30680794, 2019).
Down syndrome (7 papers, 2010 to 2024). "An example of the reverse situation is individuals with Down syndrome, who have initially increased expression of the receptors for IFN-Is (IFNAR1/2) encoded from chromosome 21." (PMID 37346050, 2023). "For example, four IFN receptor genes (IFNAR1, IFNAR2, IFNGR2, and IL10RB) and two IFN-stimulated genes (MX1 and MX2) are triplicated in Down syndrome, and individuals with Down syndrome exhibit hypersensitivity to type I IFN (IFN-I)." (PMID 38540156, 2024). "In contrast, over-expression of IFNAR1 and IFNAR2, as is the case in Down's Syndrome patients, where chromosome 21 is trisomic, results in an enhanced sensitivity to IFN." (PMID 21085662, 2010).
Flavivirus Infections (7 papers, 2016 to 2025). Infections with viruses of the genus FLAVIVIRUS, family FLAVIVIRIDAE. "We first used mice deficient in type I interferon receptor (IFNAR1 KO mice), as these are highly susceptible to flavivirus infection and disease progression." (PMID 35073759, 2022). "Mice were rendered susceptible to USUV with a dose of anti-IFNAR1 antibody prior to challenge, a strategy that was used for other wild-type mice subject to flavivirus infections including USUV." (PMID 34960621, 2021). "Currently, IFNAR1-KO and AG129 (deficient in both interferon α/β and γ receptors) mice represent well-established flavivirus infection models." (PMID 40855992, 2025). "Our findings add to previous studies using transient IFNAR1 blockade to develop mouse models of flavivirus infections." (PMID 37112795, 2023).
HIV-1 infection (7 papers, 2016 to 2025). The type species of lentivirus and the etiologic agent of acquired immunodeficiency syndrome (AIDS). "Further studies will be needed to understand the roles of IFN-α, IFN-β, and IFNAR1/2 in modulating the expression of S1PR1 in the context of HIV-1 infection." (PMID 37762169, 2023). "Aspects of the IFN-I pathway shown to be altered during productive HIV-1 infection, including IFN-I cytokines (IFNα/β), IFNAR1, and the antiviral ISGs, MHC-I, Interferon stimulated gene-15 (ISG15), and PKR, were investigated." (PMID 27613235, 2016).
liver disease (7 papers, 2010 to 2023). "Finally, when IFN-I signaling was blocked with an IFNAR1 mAb in HIV/cART mice, it efficiently prevented the development of liver diseases, including reduced pathogenic macrophages and resolved fibrosis in the liver." (PMID 35639478, 2022). "A study using interferon receptor 1 (Ifnar1) knockout mice showed that type I IFN signaling in adipocytes and hepatocytes protected against high-fat diet-induced metabolic dysregulation or methionine-choline-deficient (MCD) diet-induced hepatic disease." (PMID 34832960, 2021). "Chronic liver disease, whether due to viral or non-viral causes, reduces expression of IFNAR1 and suggests suppression of host innate immunity and liver disease progression." (PMID 25265476, 2014). "Furthermore, BRISC is also essential for the optimal activation of IFNAR1 and NLRP3 inflammasome pathways in hepatic macrophages, both of which are involved in the pathogenesis of a wide variety of liver diseases." (PMID 37968261, 2023). "Mavs-/- and Irf3-/-Irf7-/- mice, both of which lack the signaling downstream of RLRs required for virus-induced IFN synthesis, are just as permissive for infection as Ifnar1-/- mice, but they do not develop liver disease when infected with HAV." (PMID 34591933, 2021). "IRF3 mediates pathology independently of downstream IFN signaling, as Ifnar1-/- mice are not protected against ethanol-related liver injury or HAV-induced liver disease." (PMID 34591933, 2021).
tuberculosis (7 papers, 2018 to 2025). A chronic, recurrent infection caused by the bacterium Mycobacterium tuberculosis. "A cohort study of 6512 individuals showed that variations in the IFNAR1 gene can inhibit the colonization of this bacterium, leading to a decrease in palmitoleic acid production and an increased susceptibility to tuberculosis." (PMID 40710549, 2025). "Here, the authors show that genetic variation of the human IFNAR1 gene is associated with decreased susceptibility to tuberculosis and identify a role for the IFNAR1 inter-domain region in the cytokine response." (PMID 29311663, 2018). "Here, we show that genetic variation in the human IFNAR1 gene is associated with decreased susceptibility to tuberculosis and an increased risk of viral hepatitis in Chinese populations." (PMID 29311663, 2018). "Our findings suggest that IFNAR1 signaling underlies an increased risk of tuberculosis in humans and reveals a function for the IFNAR1 inter-domain region in cytokine–cytokine receptor interaction and signal transduction." (PMID 29311663, 2018). "Although the exact mechanisms by which type I IFNs exacerbate TB are not fully understood, IFNAR1 deficiency or therapeutic inhibition of type I IFN production have been shown to be host beneficial in resistance to M. tuberculosis infection in mice." (PMID 29311663, 2018). "Patients with active tuberculosis have a pronounced ISG signature in their blood cells, and Ifnar1-/- mice are better equipped to clear Mtb from the lungs, though this depends heavily on both the strains of mice and bacteria used." (PMID 33684179, 2021).
Arthritis (6 papers, 2013 to 2025). Inflammation of a joint. "This is demonstrated in murine CIA models, where ICI combinations counteract tumor-induced arthritis suppression by upregulating Ifnar1 and modifying the IL-6/IFN-γ ratio." (PMID 41239350, 2025).
bladder cancer (6 papers, 2011 to 2026). "Protein levels of interferon receptors genes (IFNAR1 and 2) were shown to be down-regulated in bladder cancer, and associated with advanced stage and resistance to chemotherapy." (PMID 24367615, 2013). "Another study showed that down-regulation of IFNAR1 sensitized bladder cancer cells to VSV-induced cell death." (PMID 22194884, 2011). "Furthermore, HC-5404 and anti-PD-1 combination therapy significantly enhanced antitumor efficacy in a syngeneic mouse bladder cancer model, correlated with increased immune activation markers on tumor cells and TAMs, including IFNAR1 and calreticulin, and reduced immunosuppressive activity of MDSCs." (PMID 41372991, 2025).
Cognitive impairment (6 papers, 2021 to 2025). Abnormal cognition is characterized by deficits in thinking, reasoning, or remembering. "Microglial IFNAR1 is involved in the development of cognitive impairment and anxiety associated with multiple diseases." (PMID 38956653, 2024). "In AD mice, long-term blockade of microglial IFNAR1 reduces cell proliferation and inflammation, thereby attenuating synaptic damage and cognitive impairment." (PMID 38956653, 2024). "Other studies have also reported that the IFNAR1 pathway is involved in the development of cognitive impairment and anxiety in several neurological diseases." (PMID 38956653, 2024). "TBI-induced cognitive deficits 7 dpi were IFNAR1 independent." (PMID 40034431, 2025). "Collectively, TBI-associated cognitive deficits and inflammatory mRNA expression in the cortex 7 dpi were independent of IFNAR1." (PMID 40034431, 2025). "One notable finding of this study was that global IFNAR1 knockout did not reduce cortical inflammation or cognitive impairment 7 dpi." (PMID 40034431, 2025). "Here, global IFNAR1 knockout did not reduce cortical in ammation or cognitive impairment 7 dpi." (PMID 40034431, 2025). "Thus, TREM2 upregulation or IFNAR1 inhibition may serve as an effective treatment for cognitive impairment in patients with various neurological or non-neurological disorders." (PMID 38956653, 2024). "Tissue specific activation of the interferon alpha and beta receptor subunit 1 (IFNAR1) and the C-X-C Motif Chemokine Ligand 10 - C-X-C Motif Chemokine Receptor 3 (CXLC10-CXCR3) axis in murine brain endothelial and epithelial cells may manifest as cognitive impairment." (PMID 38562226, 2024).
lung carcinoma (6 papers, 2018 to 2022). "In mice, the metastatic spread of mammary or lung carcinoma has been shown to be accelerated in Ifnar1-/- mice." (PMID 35833131, 2022). "The protein levels of PDL1, IRF1, IRF7, STAT1, STAT2, IFNAR1, eIF2α, and ATF4 in the normal and tumor tissues of 27 subjects with lung cancer were determined by Western blot." (PMID 30305853, 2018).
multiple sclerosis (6 papers, 2010 to 2022). A progressive autoimmune disorder affecting the central nervous system resulting in demyelination. "Polymorphisms in IFNAR1 have also been reported to be associated with susceptibility of multiple sclerosis, hepatocellular carcinoma and outcome of hepatitis B virus infection." (PMID 25350395, 2014). "Moreover, the expression levels of both the receptor subunits IFNAR1 and IFNAR2 are associated with the INF-β treatment outcome in multiple sclerosis patients." (PMID 29713327, 2018). "Interferon beta-1b (Betaseron/Extavia) is a recombinant human interferon that binds to type I interferon receptors (IFNAR1 and IFNAR2) and is FDA-approved as an immunosuppressant to treat relapsing-remitting forms of multiple sclerosis." (PMID 35628390, 2022).
pancreatic cancer (6 papers, 2014 to 2025). "Then, PTPN11 was accumulated, and an oncogene IFNAR1 was upregulated, increasing the proliferation of pancreatic cancer cells." (PMID 37670967, 2023).
Parkinson disease (6 papers, 2019 to 2026). A progressive degenerative disorder of the central nervous system characterized by loss of dopamine producing neurons in the substantia nigra and the presence of Lewy bodies in the substantia nigra and locus coeruleus. "Both Il1b and Tnfa are reported to be elevated in the MPTP model of Parkinson's disease, and IFNAR1 deficiency was also shown to reverse these, although fold‐increases in these transcripts were relatively small and rather variable." (PMID 30680794, 2019). "Two significant gene clusters (clusters 7 and 73) included genes previously associated with Parkinsonism (FIG4 and VAC14) and IBD (IFNAR1, IL6ST, ATG16L1, and NOD2)." (PMID 38741190, 2024). "Others reported recently in a mouse model that lack of IFNβ signaling via IFNAR1 caused Lewy body formation, motor and cognitive learning impairments, reduction in dopaminergic neurons, defective dopamine signaling, and a Parkinson’s disease phenotype." (PMID 32727588, 2020). "With respect to chronic neurodegenerative processes, IFNAR1 deficiency resulted in modestly slowed disease progression in SOD1(G93A) model of amyotrophic lateral sclerosis and reduced dopaminergic cell death in the MPTP model of Parkinson's disease." (PMID 30680794, 2019).
sarcoma (6 papers, 2012 to 2025). A usually aggressive malignant neoplasm of the soft tissue or bone. "In spite of being insensitive to IFNα/β, 4 of 11 IFNAR1-deficient MCA-induced sarcomas were rejected when transplanted into wild type recipients." (PMID 35251003, 2022). "Given that L-NAME failed to improve the antitumor efficacy of the anti-PD-1 mAb in Nos2-deficient mice, and that L-NAME had some activity against distinct clones of Ifnar1-deficient sarcomas, we postulate that the functionally relevant source of NO is likely antigen presenting cells." (PMID 31481761, 2019). "The relatively anti-PD-1-resistant MC38 and AT3 cells significantly upregulated Ifnβ1 transcription in response to IFNα whilst no significant change was observed in the anti-PD-1-sensitive MCA205WT or Ifnar1−/− sarcoma clones." (PMID 31481761, 2019). "In addition, after verifying the expression of IFNβ receptors (IFNAR1/2) in sarcoma cells, we directly treated sarcoma cells with IFNβ, showing a dose-dependent OCT4 upregulation at both the mRNA and protein levels." (PMID 40986050, 2025). "Indirect anti-tumor effects of type I IFNs were essential for the clearance of immunogenic sarcomas in IFNAR1 deficient mice, since it was dependent on the expression of IFNAR1 on hematopoietic host cells and not on tumor cells." (PMID 22402907, 2012). "Moreover, some IFNAR1-deficient sarcomas that grew in wild type recipients were not converted into highly immunogenic, non-growing tumors when IFNAR1 expression was restored." (PMID 35251003, 2022). "Besides, sarcoma cells from mice lacking IFNAR1 and IFNGR1 were only rejected when sensitivity to IFNγ was restored, not to type I IFN." (PMID 35251003, 2022).